EGFR (epidermal growth factor receptor)
Diseases named in the same sentence as EGFR in open-access papers (continued):
Sharing a sentence is not in itself a finding about the gene and the disease.
ovarian carcinoma (continued). "JAKi-induced apoptosis increased from 21% to 36% when cells were transfected with EGFR siRNA, suggesting that inhibition of EGFR potentiate the inhibitory activity of JAKi in ovarian cancer." (PMID 25928246, 2015). "To improve the clinical benefit of targeting EGFR in the treatment of ovarian cancer, we investigated the mechanism of resistance to EGFR inhibition." (PMID 25928246, 2015). "Monensin was shown to target multiple cancer-related signaling pathways such as Elk1/SRF, AP1, NFκB and STAT, and suppresses EGFR expression in ovarian cancer cells." (PMID 26639992, 2015). "One possible chemotherapeutic target of ovarian cancers would be the inhibition of the tyrosine kinase receptors, ErBb1 (EGFR) and ErBb2 (Her-2)." (PMID 26617640, 2015). "The EGFR is a receptor tyrosine kinase that is overexpressed in 30–98% of epithelial ovarian cancer and overexpression of EGFR (and its ligands) in ovarian cancer patients correlate with poor prognosis." (PMID 26351843, 2015). "Combining EGFR blockade with suppression of JAK/STAT3 signaling is more effective in inhibiting ovarian cancer growth than inhibition of either pathway alone." (PMID 25928246, 2015). "For ovarian cancer, a number of specific targets have been identified, most prominently folate receptor-α, vascular endothelial growth factor, EGFR, chemokine receptor 4, and matrix metalloproteinase." (PMID 25663888, 2015). "In the present study, we found that inhibition of EGFR in ovarian cancer cells increased phosphorylation of STAT3 in both SKOV3 and MDAH2774 cells in a time- and dose-dependent manner." (PMID 25928246, 2015). "A number of pro-survival signaling pathways is persistently activated in human ovarian cancer, including the epidermal growth factor receptor (EGFR) and janus kinase/signal transducer and activator of transcripton 3 (JAK/STAT3) pathways." (PMID 25928246, 2015). "Our results have demonstrated that monensin acts synergistically with tyrosine kinase and EGFR inhibitors, as well as currently-utilized agents such as oxaliplatin, to suppress proliferation of ovarian cancer cells." (PMID 26639992, 2015). "EGFR expression in quercetin aglycone or PAC DP-9 treated ovarian cancer cells was analyzed by immunoblotting and immunofluorescence microscopy." (PMID 25776829, 2015). "We show that SPINK1 drives ovarian cancer cell proliferation through activation of epidermal growth factor receptor (EGFR) signaling, and that SPINK1 promotes resistance to anoikis through a distinct mechanism involving protease inhibition." (PMID 26437224, 2015). "Relative to the other pathways considered in this study, targeting STAT3 appeared to be the most effective way to increase the therapeutic efficacy of anti-EGFR therapy in these ovarian cancer cells." (PMID 25928246, 2015). "Further analysis indicated that monensin acts synergistically with EGFR inhibitors and the chemotherapeutic drug oxaliplatin to inhibit cell proliferation and induce apoptosis of human ovarian cancer cells." (PMID 26639992, 2015). "In this report, we show that LSD1 is overexpressed in SKOV3, HO8910, and 3AO ovarian cancer cells, and its levels increase in parallel with increased levels of EGFR." (PMID 26489763, 2015). "Multiple molecules have previously been identified to interact or regulate NME2, such as EGFR, c-erbB-2, c-erbB-3 and sex steroid receptor in ovarian carcinomas." (PMID 25700270, 2015). "Among the molecular markers, HER2, KRAS, BRCA1, BRAF, and EGFR were independent and statistically significant prognostic factors for ovarian cancer patient outcomes." (PMID 26490766, 2015). "Significant increases in EGFR phosphorylation (pEGFR) were observed in ovarian cancer cells (OVCA 433) following 30 min (0.5 h), 1 h and 2 h treatment with 10 μM cisplatin without changes to total EGFR." (PMID 26351843, 2015).
ovarian carcinoma (continued). "Monensin was further shown to act synergistically with EGFR inhibitors and the chemotherapeutic drug oxaliplatin to inhibit cell proliferation and induce apoptosis of human ovarian cancer cells." (PMID 26639992, 2015). "We demonstrate, for the first time, that inhibition of EGFR significantly increased phosphorylation of STAT3 in ovarian cancer cells and blocking STAT3 activation led to enhanced anti-tumor activity of gefitinib both in vitro and in vivo." (PMID 25928246, 2015). "Up to 70% of ovarian cancer tumors and all histologic subtypes of ovarian cancer are EGFR-positive, making EGFR a promising therapeutic target in ovarian cancer." (PMID 25806106, 2015). "In a recent study of ovarian cancer, it was reported that HCRP-1 down-regulated expression is associated with activation of EGFR, and its expression has a significant impact on the prognostic value of EGFR expression." (PMID 26304749, 2015). "We found that treatment of human ovarian cancer cells with an EGFR inhibitor, gefitinib, resulted in increased STAT3 phosphorylation in a dose- and time-dependent manner." (PMID 25928246, 2015). "To determine the clinical relevance of our findings, we further examined EGFR expression in ten patient samples of ovarian cancer." (PMID 26639992, 2015). "Monensin acts synergistically with EGFR inhibitors and oxaliplatin to inhibit cell proliferation and induce apoptosis of ovarian cancer cells." (PMID 26639992, 2015). "Monensin suppresses multiple cancer-related pathways including Elk1/SRF, AP1, NFκB and STAT, and reduces EGFR expression in ovarian cancer cells." (PMID 26639992, 2015). "The PAFR antagonist WEB2086 was combined with the EGFR inhibitor AG1478 in ovarian cancer in vitro and in vivo." (PMID 24886678, 2014). "The crosstalk between PAFR and EGFR suggests a potentially important signaling linkage between inflammatory and growth factor signaling in ovarian cancer cells." (PMID 25261977, 2014). "Our results show that the combined inhibition of PAFR and EGFR additively inhibited ovarian cancer progression." (PMID 24886678, 2014). "Taken together, our data first demonstrated the involvement of the EGFR/ AKT and EGFR/ERK1/2 pathways in the miR-7 reversed EMT in ovarian cancer cells." (PMID 24816687, 2014). "Yet, recent clinical trials targeting EGFR using cetuximab, matuzumab, gefitinib, and erlotinib in epithelial ovarian cancer patients have shown only modest clinical responsiveness." (PMID 25261977, 2014). "Our results indicate that miR-7 exerted its effects in human ovarian cancer cells via the inactivation of the EGFR/AKT and EGFR/ERK1/2 signaling pathway." (PMID 24816687, 2014). "EGFR is expressed at high levels in ovarian cancer, where signaling through EGFR contributes to cell survival, proliferation and invasion." (PMID 25261977, 2014). "To date, EGFR targeting has shown limited antitumor effects in ovarian cancer when administered as monotherapy." (PMID 24886678, 2014). "EGFR, the main activator of MAPK cascade is overexpressed in 70% of ovarian cancers and is associated with worse prognosis, and chemoresistance." (PMID 25408231, 2014). "We next evaluated the effects of activated PAFR and EGFR on the expression of selected proteins and their activated forms, which are known to be important steps in prosurvival and proliferation pathways in ovarian cancer cells." (PMID 24886678, 2014). "EGFR is emerging as an important therapeutic target for several epithelial tumors, including ovarian cancer." (PMID 25261977, 2014). "Epidermal growth factor receptor (EGFR) overexpression and activation result in increased proliferation and migration of solid tumors including ovarian cancer." (PMID 24816687, 2014).
ovarian carcinoma (continued). "Our previous studies also showed that EGFR overexpression and activation result in increased metastasis of human ovarian cancer cells." (PMID 24816687, 2014). "We have shown that PAF stimulates ERK1/2 through different mechanisms, acting by PAFR-mediated EGFR transactivation in ovarian cancer cells." (PMID 25261977, 2014). "Our earlier study demonstrated that ovarian cancer cells express high levels of PAFR as well as that PAF can stimulate transactivation of the EGFR in ovarian cancer cells." (PMID 24721622, 2014). "Taken together, both in vitro and in vivo analyse suggest that PAFR and EGFR play an important role in the sustained growth, survival, and invasion of ovarian cancer cells." (PMID 24886678, 2014). "Epidermal growth factor receptor (EGFR) are also overexpressed in ovarian cancer and contribute to the growth of ovarian cancer cells." (PMID 25261977, 2014). "This novel combination of drugs offers a new choice for the current platinum- based regimens, but it is critical to evaluate the profile of PAFR and EGFR expression in ovarian cancer patients before the strategy is applied in the clinical setting." (PMID 24886678, 2014). "The inhibitory effects of combined use of the PAFR antagonist WEB2086 and the EGFR inhibitor AG1478 were tested in two ovarian cancer cell lines, CAOV-3 and SKOV-3 cells." (PMID 24886678, 2014). "Levels of EGFR protein expression were reduced after exposure of ovarian cancer cells to leptomycin B (LMB), suggesting that CRM1 plays a role in the intracellular transactivation of EGFR." (PMID 24595136, 2014). "EGFR overexpression and activation result in increased proliferation and migration of solid tumors including ovarian cancer." (PMID 24816687, 2014). "The most common type of ovarian cancer arises from ovarian surface epithelium, tissue that commonly expresses EGFR." (PMID 24886678, 2014). "Altogether, these observations highlight the interest in pursuing a combination therapy of an EGFR inhibitor with a BH3-mimetic molecule in ovarian cancer." (PMID 25299770, 2014). "To address this, we determined the effects on both Akt and ERK1/2 phosphorylation of transfecting the same ovarian cancer cell lines with an EGFR siRNA." (PMID 24816687, 2014). "Several studies have highlighted the importance of EGFR pathway in ovarian carcinoma leading to the use of EGFR inhibitors in clinical trials." (PMID 25299770, 2014). "Rahman and colleagues showed that there is correlation between MEK1 amplification (a downstream member of EGFR pathway) and worse progression-free survival in ovarian carcinoma patients." (PMID 25408231, 2014). "We also showed that the combined PAFR and EGFR targeting synergistically inhibited the ovarian cancer in vitro and in vivo." (PMID 25261977, 2014). "To determine the effects of PAF on EGFR transactivation in ovarian cancer cells, we used SKOV-3 for further investigations." (PMID 25261977, 2014). "These appearances were de facto ultrastructural refinements of the images of chromatin degradation highlighted with fluorescence imaging recorded in the living ovarian cancer cells treated with the anti-EGFR or anti-EGFRvIII guided vectors for the hrDNases." (PMID 24587967, 2013). "An important consideration for attaining this goal is the fact that ovarian cancer cells over-express EGFR or its mutants, what becomes the factor discriminating them from healthy cells - a potential facilitator of personalized therapy." (PMID 24587967, 2013). "Other investigators reported that a CXCL1-induced cell proliferation in ovarian cancer cells was related to transactivation of EGFR." (PMID 24376747, 2013). "Since it was shown that CXCL1 can induce proliferation in epithelial ovarian cancer cells by transactivation of EGFR, we compared EGFR transactivation in SKA and SKCXCR2 cells." (PMID 24376747, 2013).
ovarian carcinoma (continued). "In the GBM data, the involved pathways include parts of the RB signaling and RTK signaling pathways (CDKN2B, CDK4; EGFR, NF1 ), and in the ovarian carcinoma data a recurrent mutated module related to cell cycle and DNA repair (CCNE1, MYC, RAD52 ) is revealed." (PMID 24565034, 2013). "For example, a cross talk between CXCL12-activated CXCR4 and epidermal growth factor receptor (EGFR) has been proposed to link cell proliferation signals in ovarian carcinoma." (PMID 24384839, 2013). "In summary, CXCR2 expressing ovarian cancer cells potentiated NF-κB activation via EGFR-transactivated Akt signaling to induce CXCL1/2 secretion as an autocrine or paracrine growth factor." (PMID 24376747, 2013). "The overexpression of EGFR frequently occurs in ovarian cancer tissues and correlates with poor prognosis of the patients." (PMID 24321281, 2013). "For example, EGF enhances cisplatin-induced ovarian cancer cell apoptosis, and the degradation of EGFR is correlated with cisplatin-induced cytotoxicity in head and neck cancers." (PMID 23383347, 2013). "Data from our current study suggest that Lewis y antigen which is an important component of HE4 probably plays crucial roles in the proliferation, apoptosis, invasion, migration and resistance of ovarian cancer via the EGFR-MAPK signaling pathway." (PMID 23894390, 2013). "Because of the multiple signaling processes originating from EGFR activation, EGFR overexpression has been correlated with a poor prognosis and a decreased therapeutic responsiveness in patients with ovarian cancer." (PMID 23800251, 2013). "A third research group has found that GPER-1 expression predicts lower survival of 150 ovarian cancer patients only by co-expression with epidermal growth factor receptor (EGFR)." (PMID 23849542, 2013). "The EGFRvIII and EGFR over-expressing ovarian cancer cells, which were transduced with the transgenic hrDNases contained the chromatin architecture in the state of complete collapse and degradation." (PMID 24587967, 2013). "TrkB receptor also cross-talks with EGFR and enhanced EGFR signalling was observed in ovarian cancer cells in response to BDNF binding leading to cell survival signalling activation." (PMID 23670594, 2013). "Both BRCA1 and epidermal growth factor receptor (EGFR) play a critical role in ovarian cancer progression." (PMID 24321281, 2013). "The epidermal growth factor receptor (EGFR) tyrosine kinase has for example been shown to promote NF-κB dependent transcription in ovarian cancer." (PMID 23915189, 2013). "The anti-cancer pro-apoptotic function of an indole compound, 3,3′-diindolylmethane, toward ovarian cancer cells also involves the suppression of the Y845 phosphorylation of EGFR and the subsequent ERK/MAPK signaling pathway." (PMID 23702846, 2013). "Expression of both GPER and ERα along with active EGFR signaling, is required for E2-stimulated and G-1–stimulated proliferation of ovarian cancer cells." (PMID 23840305, 2013). "Our immunotherapy approach originates from a series of studies, in which T cells have been redirected to EpCam on adenocarcinomas; HER2/neu on prostate, breast, and ovarian cancer; EGFR on a variety of tumor types; and CD20 on malignant B cells." (PMID 23433400, 2013). "In summary, direct targeting of EGFR-targeted liposomes was specific and efficient in ovarian cancer cells in vitro, but tumor accumulation in vivo was comparable to that of non-targeted liposomes." (PMID 22844475, 2012). "There is increasing evidence indicating that the activation of EGFR signaling contributes to cellular invasion in ovarian cancer by a variety of mechanisms." (PMID 22479527, 2012). "In conclusion, this study shows that primary and long-term cultured ovarian cancer cells are largely resistant to anti-EGFR-targeted therapies, which correlates with the limited efficacy of clinical studies evaluating anti-EGFR-substances in ovarian cancer." (PMID 23109896, 2012).
ovarian carcinoma (continued). "In ovarian cancer clinical efficacy of anti-EGFR agents is limited by primary resistance or immune escape mechanisms." (PMID 23109896, 2012). "Our results showed that PEITC treatment substantially suppressed the phosphorylation of EGFR at Tyr-1068 as well as constitutive protein expression of EGFR in different ovarian cancer cell lines." (PMID 22952709, 2012). "Gefitinib and erlotinib, which are inhibitors of EGFR, stabilized disease in 11%–44% of patients with ovarian cancer but produced objective regression in only 4%–6% of cases." (PMID 22481926, 2012). "The EGFR expression level in ovarian carcinomas was significantly higher than that in borderline malignancies (p=0.012), although the ERα and ERβ expression in ovarian carcinomas was not significantly different from that in borderline malignancies." (PMID 23163984, 2012). "Remarkably, these metabolic genes are implicated in understanding the etiology of ovarian cancer and the development of targeted therapies against these growth factors (e.g. EGFR), to improve chemotherapy outcomes in ovarian cancer patients." (PMID 22509304, 2012). "Secondly, we wanted to determine the potential modulation of NK cell-mediated cytolysis against ovarian cancer cells in the presence of pharmacologic EGFR-inhibition." (PMID 23109896, 2012). "PEITC treatment caused significant down regulation of constitutive protein levels as well as phosphorylation of EGFR at Tyr1068 in various ovarian cancer cells." (PMID 22952709, 2012). "Our clinical results support the idea that GPR30 regulates an EGFR cascade, which is closely related to cancer cell growth and the survival of ovarian cancer patients." (PMID 23163984, 2012). "We conclude that monocytes provide accessory function for ADCC exerted by NK during antibody-based cancer immunotherapy directed against EGFR-positive ovarian cancer cells." (PMID 23036052, 2012). "The EGFR (epidermal growth factor receptor) has been suggested as a promising target since up to 70% of ovarian cancers are EGFR-positive and EGFR-overexpression is developed during cancer progression and correlated to poor prognosis." (PMID 23109896, 2012). "Targets under development include TRAIL, BCL-2 family, EGFR and VEGF, and clinical trials evaluating agents that inhibit VEGF and EGFR signaling pathways in ovarian cancer have been performed." (PMID 22296757, 2012). "ET-1 has also been shown to share this transactivation of EGFR in ovarian cancer cells or VSMCs, leading to MAPK activation and then regulating cell proliferation or COX-2 expression, respectively." (PMID 22747786, 2012). "Although the contributions of EGF and EGFR signaling have been described in ovarian cancer, the majority of studies have been performed only on high-grade ovarian cancer cells." (PMID 22479527, 2012). "Targeting EGFR and other components of metabolism has been, therefore, postulated to improve ovarian cancer therapy outcome." (PMID 22509304, 2012). "Since both EGFR and ARID3B are overexpressed in ovarian cancer we wanted to assess if there was a causal relationship between these molecules and ascertain if ARID3B is EGFR-regulated in ovarian cancer cells." (PMID 22860069, 2012). "Taken together, these results demonstrate that PEITC blocks the phosphorylation as well as reduce protein levels of EGFR in ovarian cancer cells." (PMID 22952709, 2012). "Epidermal growth factor receptor (EGFR) overexpression is associated with poor prognosis, resistance to chemotherapy and low survival rate in ovarian cancer." (PMID 22509304, 2012). "Many solid tumor types, e.g., breast, colon, pancreatic, lung, and ovarian cancers, overexpress EGFR, thereby leading to tumor progression, invasion, and metastases." (PMID 22844475, 2012). "Upon determining that ARID3B isoforms were both expressed highly in ovarian cancer cells we wanted to assess if they were regulated by EGFR." (PMID 22860069, 2012).